SPANXC (SPANX family member C)
Synonyms: CT11.3; SPANX-C; CTp11; SPANX-E; SPANXE
Tractability: No criterion of Open Targets' tractability assessment is met for any kind of drug.
Gene: Protein-coding gene on chromosome X (141,241,463 to 141,242,517, reverse strand). Ensembl gene ENSG00000198573.
Subcellular location: Cytoplasm; Nucleus
Subcellular location (Human Protein Atlas): Nucleoplasm; Vesicles
Gene Ontology:
Molecular function: protein binding
Cellular component: nucleus; cytoplasm
Homologues: Paralogues in human: SPANXD (98% identical), SPANXA1 (94% identical), SPANXA2 (94% identical), SPANXB1 (80% identical).
Diseases named in the same sentence as SPANXC in open-access papers:
SPANXC is named in the same sentence as 8 diseases in open-access papers, as found by Europe PMC text mining. Sharing a sentence is not in itself a finding about the gene and the disease. The quoted sentences say what the papers report.
gastric cancer (1 paper, 2022). A primary or metastatic malignant neoplasm involving the stomach. "Two (SPANXC/SPANX family member C, and C7ORF13 [LINC01006]/long intergenic non-protein coding RNA1006) are normally expressed in a testis-specific manner, and their expressions in gastric cancers are associated with EMT, migration, and metastasis." (PMID 35817785, 2022).
lung adenocarcinoma (1 paper, 2019). A carcinoma that arises from the lung and is characterized by the presence of malignant glandular epithelial cells. "The SPANXC was reactivated in lung adenocarcinoma (LUAD) tissues." (PMID 31483565, 2019).
SPANXC also shares sentences with these, for which no sentence is quoted: tumor (2 papers); bladder cancers (1); breast carcinoma (1); cancer (1); melanoma (1); sarcoma (1).